PRPF31 (pre-mRNA processing factor 31)
Description:
Involved in pre-mRNA splicing as component of the spliceosome. Required for the assembly of the U4/U5/U6 tri-snRNP complex, one of the building blocks of the spliceosome.
Synonyms: hPrp31; PRP31; NY-BR-99; SNRNP61; RP11
Tractability: Small molecule: a structure with a bound ligand is known; it has a binding pocket of medium quality. PROTAC: UniProt records ubiquitination sites on it; ubiquitination databases record sites on it; its protein half-life has been measured.
Gene: Protein-coding gene on chromosome 19 (54,115,410 to 54,131,719, forward strand). Ensembl gene ENSG00000105618.
Subcellular location: Nucleus; Nucleus speckle; Nucleus, Cajal body
Subcellular location (Human Protein Atlas): Nucleoplasm
Pathways (Reactome):
Metabolism of RNA: mRNA Splicing - Major Pathway
Gene Ontology:
Molecular function: identical protein binding; protein binding; protein-macromolecule adaptor activity; ribonucleoprotein complex binding; RNA binding; snRNP binding; U4 snRNA binding; U4atac snRNA binding
Biological process: mRNA splicing, via spliceosome; ribonucleoprotein complex localization; snoRNA localization; spliceosomal tri-snRNP complex assembly; spliceosomal snRNP assembly; spliceosome conformational change to release U4 (or U4atac) and U1 (or U11)
Cellular component: Cajal body; MLL1 complex; nuclear speck; nucleoplasm; nucleus; precatalytic spliceosome; spliceosomal complex; U12-type precatalytic spliceosome; U2-type precatalytic spliceosome; U4 snRNP; U4/U6 x U5 tri-snRNP complex; U4atac snRNP; spliceosomal tri-snRNP complex; U2-type spliceosomal complex; U4/U6 snRNP; U4atac/U6atac snRNP; U4atac/U6atac x U5 tri-snRNP complex
Genetic constraint (gnomAD): Loss-of-function variants: 12 observed, 55.96 expected, observed/expected ratio (o/e) 0.21, 90% interval 0.14 to 0.35. The upper end of that interval is the gene's LOEUF score, 0.35, which puts it in group 1 of 6, group 1 being the genes least tolerant of losing a copy. Missense variants: 431 observed, 671.02 expected, observed/expected ratio (o/e) 0.64, 90% interval 0.59 to 0.7. Synonymous variants: 287 observed, 276.16 expected, observed/expected ratio (o/e) 1.04, 90% interval 0.94 to 1.15.
Homologues: Orthologues: chimpanzee PRPF31 (100% identical), macaque PRPF31 (100% identical), dog PRPF31 (99% identical), rat Prpf31 (99% identical), mouse Prpf31 (99% identical), guinea pig PRPF31 (99% identical), pig PRPF31 (99% identical), tropical clawed frog prpf31 (91% identical), rabbit PRPF31 (87% identical), zebrafish prpf31 (83% identical), Drosophila melanogaster Prp31 (61% identical), Caenorhabditis elegans prp-31 (46% identical).
Diseases named in the same sentence as PRPF31 in open-access papers:
PRPF31 is named in the same sentence as 42 diseases in open-access papers, as found by Europe PMC text mining. Sharing a sentence is not in itself a finding about the gene and the disease. The quoted sentences say what the papers report.
retinitis pigmentosa (38 papers, 2008 to 2025). Retinitis pigmentosa (RP) is an inherited retinal dystrophy leading to progressive loss of the photoreceptors and retinal pigment epithelium and resulting in blindness usually after several decades. "Retinitis pigmentosa 11 is an untreatable, dominantly inherited retinal disease caused by heterozygous mutations in pre-mRNA processing factor 31 PRPF31." (PMID 38542364, 2024). "PRPF31-associated retinal dystrophy, or retinitis pigmentosa 11 (RP11), is an autosomal dominantly inherited type of retinitis pigmentosa." (PMID 36833363, 2023). "The comparison between patient-derived iPSCs, healthy donors and CRISPR-corrected controls was instrumental to delineate the molecular and cellular mechanisms underlying the pathology of PRPF31 splicing factor-related Retinitis Pigmentosa 11 (RP11)." (PMID 36499601, 2022). "Retinitis pigmentosa 11 (RP11) is caused by dominant mutations in PRPF31, however a significant proportion of mutation carriers do not develop retinopathy." (PMID 34680937, 2021). "Unexpectedly, in 2001, it was discovered that heterozygous pathogenic variants in PRPF31 are associated with retinitis pigmentosa (RP), an inherited retinal dystrophy affecting 1:2000 to 1:3500 people worldwide." (PMID 32014492, 2020). "PRPF31-associated retinitis pigmentosa presents a fascinating enigma: some mutation carriers are blind, while others are asymptomatic." (PMID 26781568, 2016). "A sentinel example of incomplete penetrance is PRPF31-associated retinitis pigmentosa, where presence of symptomatic and asymptomatic mutation carriers is a universal feature in affected families." (PMID 26781568, 2016). "For example mutations in the splicing factor gene PRPF31 can cause retinitis pigmentosa, the most prevalent inherited retinal disease triggering photoreceptor degeneration." (PMID 26985665, 2016). "Two previous studies of the effects of mutations in three splicing factors (PRPF3, PRPF8 and PRPF31) linked to retinitis pigmentosa on mRNA splicing in lymphoblast cells reported evidence of retained introns." (PMID 24969741, 2014). "Mutations in PRPF31 have been implicated in retinitis pigmentosa, a blinding disease caused by degeneration of rod photoreceptors." (PMID 25729402, 2013). "Missense mutations in the splicing factor gene PRPF31 cause a dominant form of retinitis pigmentosa (RP11) with reduced penetrance." (PMID 18431455, 2008). "A deficient PRPF31 gene is one of several retinitis pigmentosa-causing genes (see Section 11)." (PMID 33138308, 2020). "Mutations in pre-mRNA splicing factor PRPF31 can lead to retinitis pigmentosa (RP)." (PMID 31892304, 2019). "Indeed, a single-base substitution in dominant retinitis pigmentosa disease-causing gene, PRPF31, located deep within intron 13 was recently identified." (PMID 21496248, 2011). "Affecting approximately 1 in 4000 individuals worldwide, retinitis pigmentosa exhibits significant genetic heterogeneity, with mutations in genes such as RHO, PRPF31, RPE65, USH2A, and NR2E3, which contribute to its diverse clinical presentation." (PMID 40869487, 2025). "These include PRPF31‐mediated Retinitis Pigmentosa (RP11), Stargardt disease (STGD1) and Retinoblastoma (Rb)." (PMID 36177499, 2023). "AAV-mediated PRPF31 gene augmentation restored the retinal structure and function in a rapidly degenerating mouse model, demonstrating the first in vivo proof-of-concept for AAV-mediated gene therapy to treat PRPF31-retinitis pigmentosa." (PMID 36509783, 2022). "Mutations in genes encoding the splicing factors PRPF3, PRPF8, PRPF31, RP9, and SNRNP200 can cause non-syndromic retinitis pigmentosa, a severe form of inherited blindness leading to rod photoreceptor degeneration." (PMID 26985665, 2016). "Retinitis pigmentosa is also caused by mutations in components of the splicing machinery, such as U4/U6 small nuclear ribonucleoprotein Prp3 (PRPF3), PRPF8, and PRPF31, suggesting a considerable role of RNA biology in this disease." (PMID 26520658, 2015).
retinitis pigmentosa (continued). "Mutations in six spliceosomal proteins, PRPF3, PRPF4, PRPF6, PRPF8, PRPF31 and SNRNP200, cause retinitis pigmentosa (RP), a disease characterized by progressive photoreceptor degeneration." (PMID 25383878, 2014). "We included 37 individuals with a PRPF31 variant classified as pathogenic or likely pathogenic, 30 had retinitis pigmentosa (RP) and seven were non-penetrant carriers (NPC)." (PMID 36833363, 2023). "Moreover, considering particular genes, deletions decreased their expression resulting in disease phenotypes, e.g., retinitis pigmentosa (deletion of an intron of the PRPF31 gene), DiGeorge syndrome (deletions within several genes), or Fanconi anaemia (deletion in exons of the FANCA gene)." (PMID 36564645, 2022). "However, there are reports where mutations in a ubiquitously expressed protein only affects the eye, e.g., mutations in PRPF31 only cause retinitis pigmentosa and does not affect any other part of the body." (PMID 32339198, 2020). "This could possibly explain why some mouse models, e.g.Prpf31 mutants, which cause retinitis pigmentosa-11 in humans, do not exhibit photoreceptor cell death." (PMID 30345028, 2018). "Gene therapy is a promising treatment for PRPF31-retinitis pigmentosa, however, there are currently no suitable animal models in which to develop AAV-mediated gene augmentation." (PMID 36509783, 2022).
autosomal dominant retinitis pigmentosa (18 papers, 2011 to 2024). Autosomal dominant retinitis pigmentosa (RP) is an autosomally dominant inherited retinal dystrophy leading to progressive loss of the photoreceptors and retinal pigment epithelium and resulting in blindness usually after several decades. "Pre-mRNA processing factor 31 (PRPF31) is a constitutive spliceosomal component, which mutations are associated with autosomal dominant retinitis pigmentosa." (PMID 38382674, 2024). "Pre-mRNA processing factors (PRPF6, PRPF8, and PRPF31) mutated in autosomal dominant retinitis pigmentosa and were identified as regulators during ciliogenesis." (PMID 36759599, 2023). "Mutations in PRPF31 cause autosomal dominant retinitis pigmentosa, an untreatable form of blindness." (PMID 36509783, 2022). "PRPF31-associated retinopathy (RP11) is a common form of autosomal dominant retinitis pigmentosa (adRP) that exhibits wide variation in phenotype ranging from non-penetrance to early-onset RP." (PMID 34198599, 2021). "Mutations in pre-mRNAs processing factor 31 (PRPF31) cause autosomal dominant retinitis pigmentosa, a progressive retinal degeneration disease." (PMID 33476374, 2021). "Mutations in PRPF31 are the second most common cause of the degenerative retinal ciliopathy autosomal dominant retinitis pigmentosa." (PMID 33095315, 2021). "Pathogenic variants in pre-messenger RNA (pre-mRNA) splicing factor 31, PRPF31, are the second most common genetic cause of autosomal dominant retinitis pigmentosa (adRP) in most populations." (PMID 32014492, 2020). "•PRPF31 is the second most common cause of autosomal dominant retinitis pigmentosa and a potential target for gene therapy." (PMID 32014492, 2020). "Monoallelic variants in PRPF31 are a common cause of autosomal dominant retinitis pigmentosa (adRP) with incomplete penetrance." (PMID 30967900, 2019). "Mutations in PRPF31 have been repeatedly found to be associated with autosomal dominant retinitis pigmentosa (adRP)." (PMID 24244300, 2013). "Heterozygous mutations in the PRPF31 gene cause autosomal dominant retinitis pigmentosa (adRP), a hereditary disorder leading to progressive blindness." (PMID 23144630, 2012). "Mutations in the ubiquitously expressed splicing factor PRPF31 are found in 8% of patients suffering from autosomal-dominant Retinitis Pigmentosa (ad-RP;)." (PMID 21801444, 2011). "For patients with autosomal dominant retinitis pigmentosa (RP), the most frequently associated genes were RHO, RP1, and PRPF31; for X-linked and autosomal recessive forms of RP, the most frequently associated genes were RPGR and USH2A, respectively." (PMID 32423767, 2020). "At least six different proteins of the spliceosome, including PRPF3, PRPF4, PRPF6, PRPF8, PRPF31, and SNRNP200, are mutated in autosomal dominant retinitis pigmentosa (adRP)." (PMID 30967900, 2019). "Moreover, a proof-of-concept for dominant retinitis pigmentosa due to haploinsufficiency rescued phagocytosis and cilia formation by AAV2/Anc80-PRPF31 in hiPSC-derived PRPF31+/− RPE cells." (PMID 32545533, 2020).
retinal degeneration (16 papers, 2011 to 2025). Degeneration of the retina. "A haploinsufficient and dominant-negative mechanism is involved in retinal degeneration associated with PRPF31 mutations." (PMID 38999417, 2024). "Here, we establish Prpf31 mutant RP mouse models through the delivery of AAV-CRISPR/Cas9 and characterize the resulting retinal degeneration caused by Prpf31-KO." (PMID 36509783, 2022). "To better understand the molecular mechanisms underlying retinal degeneration caused by Prpf31 KO, we quantified the mRNA expression of marker genes of temporal retina from KO and PBS-injected eyes 1, 2, 3, 4 weeks and 10 weeks (p.i.)." (PMID 36509783, 2022). "To explore possible mechanisms underlying retinal degeneration caused by mutations in regulators of the splicing machinery, we induced mutations in Drosophila Prp31, the orthologue of human PRPF31, mutations in which are associated with RP11." (PMID 33495354, 2021). "To better understand the role of Prpf31 in retinal degeneration, we have used heterozygous Prpf31A216P/+ KI mice, a mouse model which carries the point-mutation p.A216P in the Prpf31 gene, known to be responsible for adRP in humans." (PMID 31892304, 2019). "In conclusion, our data provide a detailed mechanistic explanation of retinal-specific phenotypes in PRPF31-mutated RP type 11 and, more generally, the characterisation of potential pathomechanisms during retinal degeneration." (PMID 30315276, 2018). "Protein aggregation leads to the overexpression of HSP70, which may offer a novel therapeutic target for treating retinal degeneration caused by PRPF31 mutations." (PMID 38999417, 2024). "Here, we aimed to establish a more meaningful Drosophila model for RP11-associated retinal degeneration, a human disease associated with mutations in the human orthologue PRPF31, which would allow a deeper insight into the role of this splicing factor in the origin and progression of the disease." (PMID 33495354, 2021). "Furthermore, the mutation of ubiquitously expressed and highly conserved splicing factors PRPF6, PRPF8, and PRPF31 causes retinal degeneration, suggesting a specialized role of the splicing machinery in the retina." (PMID 27151457, 2016). "Here, the authors show that CRISPR-Cas9 editing of the Prpf31 gene in mice leads to retinal degeneration similar to human patients, and, in the same model, demonstrate benefits from PRPF31 gene therapy." (PMID 36509783, 2022). "With the emerging role of enzymes involved in tubulin glycylation and glutamylation in retinal degeneration, the clinical and cellular phenotype associated with PRPF6 and PRPF31 mutations, TTLL3 is an extremely interesting candidate for further investigation." (PMID 36176300, 2022). "In asymptomatic carriers CNOT3 is expressed at low levels, allowing higher amounts of wild-type PRPF31 transcripts to be produced and preventing manifestation of retinal degeneration." (PMID 23144630, 2012). "Although haploinsufficiency contributes to the physiopathology of the disease, it is still not clear how retinal degeneration occurs in patients carrying PRPF31 mutations." (PMID 31892304, 2019). "Attempts to generate mouse models of PRPF31-associated adRP have failed to yield animals with a retinal degeneration phenotype." (PMID 25729402, 2013). "Heterozygous mice with one copy of the PRPF3 or PRPF31 genes knocked out do not cause retinal degeneration." (PMID 21283520, 2011). "Here we establish Prpf31 mutant mouse models using AAV-mediated CRISPR/Cas9 knockout, and characterize the resulting retinal degeneration phenotype." (PMID 36509783, 2022). "In this study UV exposure is used as a research tool to investigate the effect of DNA damage on PRPF6 and PRPF31 mutant cells, but oxidative stress, from the high level of reactive oxygen species in the RPE cells, plays more of a role in retinal degeneration in vivo." (PMID 36176300, 2022).
retinal degeneration (continued). "Neither Prpf31 knock-in animals nor knock-out animals displayed retinal degeneration, and the animals did not have any visual defect at up to 18 months of age." (PMID 25729402, 2013).
retinal disease (7 papers, 2007 to 2025). "In conclusion, the application of splice-switching AOs was extended to inherited retinal disease caused by a specific PRPF31 mutation by targeting the removal of PRPF31 exon 12 that harbors a PTC and restoring the open reading frame during pre-mRNA processing." (PMID 38542364, 2024). "An example of delivery of a possible therapeutic transgene was shown, driving its expression to the RPE, which is the target cell type for many retinal diseases, including PRPF31-RP." (PMID 35456263, 2022). "In support of this, a recent Korean national study demonstrated the utility of WGS in inherited retinal diseases by identifying large deletions in IQCB1 and PRPF31 that were missed by WES or panel testing." (PMID 40725491, 2025). "Although inheritance of a single PRPF31 null allele is associated with the development of RP11 in the majority of patients (75–95%, depending on the population studied), most reported RP11 cohorts included individuals who carried the pathogenic mutation but did not develop retinal disease." (PMID 34680937, 2021).
Retinal dystrophy (4 papers, 2015 to 2021). Retinal dystrophy is an abnormality of the retina associated with a hereditary process. "Of the 24 missense variants in PRPF31 labelled ‘uncertain significance’ in patients with RP or retinal dystrophy in ClinVar, our assessment following ACMG/AMG guidelines confirmed that all are VUS." (PMID 33095315, 2021). "This study allowed the identification of the genetic cause of the retinal dystrophy and the establishment of a correct diagnosis in four families, including a large heterozygous deletion in PRPF31, typically considered one of the pitfalls of this method." (PMID 26197217, 2015). "HSP70 plays an important role in retinal dystrophies, including RP so we have also evaluated the distribution and expression of HSP70 protein in the ARPE-19 cells overexpressing either PRPF31-GFP or A216P-GFP by immunofluorescence and Western blotting." (PMID 31892304, 2019).
Blindness (3 papers, 2013 to 2022). Blindness is the condition of lacking visual perception defined as a profound reduction in visual perception. "Here we present a fly model for RP11, an autosomal-dominant human disease caused by mutations in the splicing regulator PRPF31, which leads to blindness in affected patients." (PMID 33495354, 2021). "A PRPF31 heterozygous mutation carrier can be asymptomatic if the wild-type (WT) allele produces sufficient PRPF31 for normal retinal function, or can progress to blindness if remaining PRPF31 levels fall beneath a critical threshold." (PMID 36509783, 2022).
Stargardt disease (3 papers, 2020 to 2023). "These genes are known to cause: X-linked RP (RPGR), autosomal recessive RP (MAK and EYS), autosomal dominant RP (PRPF31), Stargardt disease (ABCA4), and Leber congenital amaurosis (GUCY2D)." (PMID 32000842, 2020).
macular degeneration (2 papers, 2013 to 2019). Loss of vision in the central portion of the retina (macula), secondary to retinal degeneration. "For these reasons, we suggest that primary RPE degeneration phenotype with drusen-like deposits present in these Prpf31 mutant mice could be due to splicing defects in genes that could be associated with macular degenerative diseases such as ABCA4." (PMID 31892304, 2019).
myopia (2 papers, 2012 to 2025). "Although one of the obligate carriers with a relatively large deletion of the PRPF31 gene exhibited clear evidence of high myopia, given the high prevalence of myopia in East Asia, this finding could simply be a coincidence." (PMID 23288994, 2012).
Rod-cone dystrophy (2 papers, 2022 to 2024). An inherited retinal disease subtype in which the rod photoreceptors appear to be more severely affected than the cone photoreceptors. "Why pathogenic variants in such ubiquitously expressed genes give only a rod-cone dystrophy is still not clear: rod photoreceptors appear uniquely vulnerable to loss of function in one PRPF31 allele." (PMID 36161854, 2022).
ciliopathies (1 paper, 2021). "We hope that this will be a useful tool for clinical characterisation of PRPF31 variants of uncertain significance, and can be extended to variant classification in other ciliopathies." (PMID 33095315, 2021).